ANGPTL2 (angiopoietin like 2)
Description:
Induces sprouting in endothelial cells through an autocrine and paracrine action.
Synonyms: ARP2; HARP
Tractability: Antibody: UniProt places it where antibodies can reach, with medium confidence; UniProt predicts a signal peptide or a membrane-spanning region; its Gene Ontology location is reachable by antibodies, with medium confidence.
Gene: Protein-coding gene on chromosome 9 (127,087,348 to 127,122,645, reverse strand). Ensembl gene ENSG00000136859.
Subcellular location: Secreted
Subcellular location (Human Protein Atlas): Golgi apparatus; Predicted to be secreted
Gene Ontology:
Molecular function: protein binding; signaling receptor binding
Biological process: cell-cell signaling; blood coagulation
Cellular component: extracellular exosome; extracellular matrix; extracellular region
Genetic constraint (gnomAD): Loss-of-function variants: 25 observed, 54.33 expected, observed/expected ratio (o/e) 0.46, 90% interval 0.33 to 0.64. The upper end of that interval is the gene's LOEUF score, 0.64, which puts it in group 2 of 6, group 1 being the genes least tolerant of losing a copy. Missense variants: 545 observed, 681.6 expected, observed/expected ratio (o/e) 0.8, 90% interval 0.75 to 0.86. Synonymous variants: 276 observed, 287.09 expected, observed/expected ratio (o/e) 0.96, 90% interval 0.87 to 1.06.
Homologues: Orthologues: chimpanzee ANGPTL2 (99% identical), macaque ANGPTL2 (99% identical), pig ANGPTL2 (98% identical), rabbit ANGPTL2 (97% identical), dog ANGPTL2 (97% identical), guinea pig ANGPTL2 (97% identical), mouse Angptl2 (95% identical), rat Angptl2 (95% identical), tropical clawed frog angptl2 (84% identical). Paralogues in human: ANGPTL1 (57% identical), ANGPTL6 (43% identical), TNC (28% identical), TNR (28% identical), ANGPT1 (27% identical), TNXB (27% identical), ANGPT2 (27% identical), FIBCD1 (26% identical), ANGPT4 (26% identical), FGB (25% identical), ANGPTL3 (24% identical), FGG (23% identical), and 13 more.
Diseases named in the same sentence as ANGPTL2 in open-access papers:
ANGPTL2 is named in the same sentence as 144 diseases in open-access papers, as found by Europe PMC text mining. Sharing a sentence is not in itself a finding about the gene and the disease. The quoted sentences say what the papers report.
Obesity (42 papers, 2012 to 2026). Accumulation of substantial excess body fat. "ANGPTL2 has been reported to regulate chronic inflammation and metabolic abnormalities in obesity, and abnormal expression of ANGPTL2 is associated with multiple tumors." (PMID 36865085, 2023). "Nevertheless, ANGPTL2 is known to mediate chronic inflammation and promote obesity-associated insulin resistance in adipose tissues." (PMID 35747760, 2022). "ANGPTL2 has been linked with obesity-related cancers in humans, for instance colorectal cancer and has been shown to increase angiogenesis by increasing VEGF-A and Ang II in osteosarcoma mouse models." (PMID 36038791, 2022). "ANGPTL2 was also found to be associated with obesity and insulin resistance, and to positively correlate with TGL levels." (PMID 31396158, 2019). "The present study was undertaken to determine the pattern and regulation of ANGPTL2 expression in human adipose tissue in the context of obesity and associated diseases." (PMID 30228336, 2018). "If so, younger age in nondiabetic obese group can cause to underestimate the influence of obesity on the adipose tissue ANGPTL2 mRNA or serum ANGPTL2 levels." (PMID 30228336, 2018). "Our data from a combination of in vivo and in vitro cell culture experiments support the contention that ANGPTL2 production by adipocytes is increased by alterations in the microenvironment, especially ER stress, which are caused by obesity." (PMID 30228336, 2018). "We have shown that aberrant ANGPTL2 signaling causes chronic inflammatory diseases, such as obesity, metabolic disease, type 2 diabetes, atherosclerotic disease, and possibly some cancers." (PMID 28043948, 2017). "Recently, we reported that aberrant angiopoietin‐like protein 2 (ANGPTL2) signaling causes chronic inflammatory diseases, such as obesity, metabolic disease, type 2 diabetes, atherosclerotic disease, and possibly some cancers." (PMID 28043948, 2017). "Angptl2 has been linked to tumor development, migration and metastasis of the tumor cells, obesity (21, –, 23), and cardiovascular disorders (24, –, 26)." (PMID 26839315, 2016). "The present study supports this hypothesis, as ANGPTL2 deficiency reduced inflammation across multiple organs and attenuated obesity‐induced cardiac dysfunction, kidney fibrosis, and adipocyte hypertrophy." (PMID 41508557, 2026). "An excess of ANGPTL2 causes chronic inflammation by activating NF-κB inflammatory signalling through integrin α5β1 and irreversible tissue remodelling associated with the progression of metabolic diseases, such as obesity, type 2 diabetes, and atherosclerosis." (PMID 40243889, 2025). "Thus, ANGPTL2 plays a key role in the mechanism underlying adipose tissue inflammation, which is involved in the pathogenesis of the IR associated with obesity." (PMID 37189824, 2023). "Angptl2 is an inflammatory mediator specifically associated with an unfavorable metabolic milieu, such as obesity, type 2 diabetes, and hypertriglyceridemia, hence promoting insulin resistance and endothelial inflammation, which are associated with atherosclerosis and heart failure." (PMID 32732919, 2020). "Because ANGPTL2 and obestatin were reported to be associated with insulin resistance, diabetes and obesity and due to the role of ANGPTL2 in inflammation, we hypothesized that they may also play a role in underlying pathogenic mechanisms which leads to PCOS." (PMID 29932432, 2018). "However, ANGPTL2 overexpression can cause chronic inflammation and subsequent irreversible pathological tissue remodeling, and is associated with obesity, metabolic disease, type 2 diabetes, atherosclerosis, and possibly some cancers." (PMID 26397985, 2015). "In addition, the possible association of serum ANGPTL2 and miR-124-3p with obesity, inflammation, insulin resistance, and endocrine hormone levels in PCOS patients, and their potential to serve as biomarkers for the diagnosis of PCOS remain to be further studied." (PMID 35747760, 2022).
Obesity (continued). "In summary, our findings highlight the dual roles of ANGPTL2 in inflammation, tissue homeostasis, and immune regulation, indicating its context‐dependent functions in aging, obesity, and chronic disease." (PMID 41508557, 2026). "Because we previously reported that deletion of ANGPTL2 reduces adipose tissue inflammation and systemic insulin resistance in dietary obesity, we further investigated a possible role of ANGPTL2 in HFD‐induced adipose tissue remodeling." (PMID 41508557, 2026). "Recent findings suggest that ANGPTL-2 is a key mediator linking obesity to systemic insulin resistance, playing a crucial role in both atherosclerosis and the development of diabetes." (PMID 41026696, 2025). "In patients with diabetes and obesity, ANGPTL2 produced by adipocytes, infiltrated macrophages, and endothelial cells, leading to an inflammatory response through activation of the integrin α5β1/Rac1 NFκB pathway resulting in inflammatory gene expression." (PMID 37189824, 2023). "This glycoprotein was described as an adipose receptor for angiopoietin-like protein 2 (ANGPTL2), which is involved in obesity-related chronic inflammation." (PMID 37898403, 2023). "CD146 is known to be an endothelial/pericyte marker that acts as a receptor for angiopoietin-like protein 2 (ANGPTL2) and has been implicated in promoting obesity by enhancing adipogenesis and lipogenesis." (PMID 36551837, 2022). "Existing evidence further indicates that ANGPTL2 is an essential inflammatory mediator derived from adipocytes, which links systemic insulin resistance to obesity and induces inflammation and insulin resistance." (PMID 35747760, 2022). "Of these top candidate proteins, only ANGPTL2 has been reported to play an important role in obesity and related diseases and its adipose receptor has not been identified; therefore, we decided to focus on ANGPTL2." (PMID 33747748, 2021). "ANGPTL2 maintains vascular endothelium homeostasis, having a role in angiogenesis, tissue repair, obesity and atherosclerotic diseases." (PMID 33836805, 2021). "Adipocyte, macrophage-derived Angptl2 is a key mediator linking obesity and the related metabolic diseases to the inflammatory response in adipose tissues." (PMID 32429849, 2020). "As obesity progresses, proinflammatory adipokines, including leptin, TNF, resistin, IL-6, RBP4, lipocalin-2, and ANGPTL-2, are preferentially synthesized and cause chronic inflammation." (PMID 33133214, 2020). "Angptl2 is upregulated in obesity and type 2 diabetes and accelerates endothelial inflammation, atherosclerosis, and the pathogenesis of heart failure." (PMID 32732919, 2020). "Angiopoietin-like protein 2 (ANGPTL2) is a pro-inflammatory adipokine that is upregulated in obesity and is important in the progression of atherosclerosis and cardiovascular disease." (PMID 31743976, 2019). "In conclusion, the present study shows, for the first time to our knowledge, the pattern and regulation of ANGPTL2 expression in human adipose tissue in the context of obesity and type 2 diabetes." (PMID 30228336, 2018). "As a result, ANGPTL2 has been proposed as a key adipocyte-derived inflammatory mediator linking obesity to systemic insulin resistance." (PMID 30228336, 2018). "It is likely that ANGPTL2 derived from different cell types cooperates and synergizes to favour the pathogenesis of one chronic disease, but one cell type may also be predominantly implicated, such as adipocytes in obesity and diabetes and kidney cells in chronic kidney disease." (PMID 29138671, 2017). "The tissue expression of Angptl2 increases significantly with aging and is related to obesity, rheumatoid arthritis, and diabetes, disorders that all progress with age." (PMID 26839315, 2016). "In cases of severe obesity, ANGPTL2 expression is abundant in adipose tissues and excess signaling by ANGPTLs leads to chronic inflammation, resulting in metabolic diseases such as obesity-related insulin resistance and type 2 diabetes." (PMID 25889082, 2015).
Obesity (continued). "Obesity have been demonstrated to induce adipose tissue inflammation, which further promote ANGPTL2 overexpression." (PMID 26397985, 2015). "Our current findings thus support the previously suggested possibility that circulating ANGPTL2 levels can serve as a marker of obesity-induced metabolic abnormalities as well as atherosclerosis." (PMID 25889082, 2015). "This close relationship between ANGPTL2 and hsCRP further implicates that ANGPTL2 is one of key adipocyte-derived inflammatory mediators linking obesity to related metabolic diseases." (PMID 25889082, 2015). "In mice and human studies, ANGPTL2 is abundantly expressed in adipose tissues as a key mediator that links obesity, adipose tissue inflammation, and systemic insulin resistance." (PMID 26397985, 2015). "In humans, the ANGPTL2 concentration in the circulation is up-regulated in obesity (particularly visceral obesity) and is correlated with the levels of systemic insulin resistance." (PMID 25889082, 2015). "In humans, ANGPTL2 concentration is upregulated in obesity and correlated with both systemic insulin resistance and inflammation levels." (PMID 26397985, 2015). "Angiopoietin-like protein 2 (ANGPTL2), which is mainly expressed from adipose tissue, is demonstrated to be involved in obesity, metabolic syndrome, and atherosclerosis." (PMID 26397985, 2015). "ANGPTL2 is a key adipocyte-derived inflammatory mediator linking obesity to systemic insulin resistance." (PMID 23837045, 2013). "Notably, we recently reported that obesity‐induced chronic inflammation, facilitated by high ANGPTL2 expression, suppresses the efficacy of ICIs." (PMID 41508557, 2026). "For example, ANGPTL-2 mediates obesity and related metabolic diseases." (PMID 39479393, 2024). "Because obesity, IR, and inflammation have been involved as key pathogenetic factors of HS, we hypothesized that raised serum ANGPTL2 levels could be related to HS severity." (PMID 37189824, 2023). "Besides, ANGPTL2 has been reported in a series of metabolic disorders such as obesity, inflammation, insulin resistance, lipid metabolism disorder, and malignancies." (PMID 35747760, 2022). "The expression of angiopoietin-like 2 is elevated in obesity and related pathological conditions." (PMID 34228231, 2021). "As an association between centenarian age and insulin sensitivity has been reported, and centenarian have a very low prevalence of diabetes and obesity, centenarians may exhibit resistance against Angptl2-mediated proinflammatory processes." (PMID 32732919, 2020). "ANGPTL2 was reported as a key inflammatory mediator derived from the adipose tissue, and the changes in ANGPTL2 protein levels in blood circulation could be used as a marker for metabolic abnormalities to induce obesity." (PMID 32988397, 2020). "Visceral adipose tissue accumulation also promotes an increase in the secretion of angiopoietin-like protein 2 (Angptl2), a pro-inflammatory factor derived from adipocytes and considered a key mediator of chronic adipose tissue inflammation and obesity-related systemic insulin resistance." (PMID 29618983, 2018). "Thus, our data confirm that adipocytes are the main cells responsible for the over-production of ANGPTL2 in human adipose tissue during obesity." (PMID 30228336, 2018). "Conversely, adipocyte hypertrophy per se, resulting from over-accumulation of lipids, might also increase ANGPTL2 expression in obesity, because ANGPTL2 expression is induced during adipogenesis." (PMID 30228336, 2018). "ANGPTL2 is known as an inflammatory mediator derived from adipose tissue that links obesity to systemic insulin resistance, and obestatin has been identified as a hormone associated with insulin resistance that suppresses food reabsorption, inhibits gastric emptying and decreases weight gain." (PMID 29932432, 2018).
Obesity (continued). "In addition, to understand better how ANGPTL2 expression is induced in obesity, we incubated differentiated human adipocytes in a series of culture environments mimicking obesity." (PMID 30228336, 2018). "We next asked what stimulates ANGPTL2 production by adipocytes during obesity." (PMID 30228336, 2018). "Among ANGPTLs, ANGPTL2 can be considered a key mediator that links obesity and atherosclerosis." (PMID 26739706, 2016). "Finally, it should be mentioned the angiopoietin-related protein 2 (ANGPTL2) that was described as key adipocyte-derived inflammatory mediator that links obesity to systemic insulin resistance." (PMID 26198096, 2015). "In fact, a rise in circulating ANGPTL2 levels bears a close association with C-reactive protein expression in obesity and an increase in expression of pro-inflammatory TNF-α and its receptor TNFR1 in the onset and progression of T2D, obesity, and heart failure." (PMID 40427505, 2025). "Thus, adipocyte-derived inflammatory ANGPTL2 has been proposed to link obesity to IR." (PMID 37189824, 2023). "In adipose tissues, ANGPTL2 mediates chronic inflammation of adipose tissue and promotes obesity-related IR, but whether ANGPTL2 mediates IR through the PI3K/Akt signal transduction pathway in affecting the follicular development has not been reported previously." (PMID 32988397, 2020). "Thus, adipocyte-derived inflammatory ANGPTL2 was proposed to link obesity to insulin resistance." (PMID 29138671, 2017). "Furthermore, increased levels of ANGPTL2 were reported in diabetes, chronic kidney disease, cardiovascular diseases, metabolic disorders including obesity, and other diseases, including autoimmune diseases such as dermatomyositis and rheumatoid arthritis." (PMID 29138671, 2017). "Although further studies are needed to reveal the role of ANGPTL2 in the pathogenesis of type 2 diabetes, these earlier results and our present findings suggest the possibility that ANGPTL2 might be one of key mediators that link obesity and type 2 diabetes." (PMID 25889082, 2015). "Since serum ANGPTL2 leves links obesity with systemic insulin resistance and is positively associated with the development of T2DM, our results suggest that β-receptor activation helps to maintain the metabolic profile of MHO and prevent T2DM by decreasing serum ANGPTL2 levels." (PMID 23837045, 2013). "In addition, ANGPTL2 represents a key inflammatory mediator from adipose tissues, and alternation in circulating ANGPTL2 protein levels serves as a marker for metabolic abnormalities, inducing obesity and promoting chronic adipose tissue inflammation and obesity-related systemic insulin resistance." (PMID 35747760, 2022). "Together, these findings demonstrate that ANGPTL2 directly affects adipocytes via CD146 to promote obesity, suggesting that CD146 can be a potential target for treating obesity." (PMID 33747748, 2021). "Circulating levels of ANGPTL2 are also positively correlated with levels of the proinflammatory cytokine TNFα or its receptor TNFR1 in diabetes, obesity, and heart failure." (PMID 29138671, 2017). "ANGPTL2, a member of the ANGPTL family, has been shown to be expressed abundantly in adipose tissues and is reportedly a key mediator linking obesity to adipose tissue inflammation and systemic insulin resistance in mice and humans." (PMID 23837045, 2013). "Given that ANGPTL2 expression is upregulated in aging and obesity, particularly in adipocytes and macrophages within adipose tissue, its role as a SASP factor is particularly relevant in obesity‐induced metabolic inflammation." (PMID 41508557, 2026). "These in vitro and clinical studies suggested that Angptl2 is involved in the pathophysiology of metabolic syndrome, such as obesity, although no reports are available about the roles of Angptl1 in adipobiology." (PMID 33910546, 2021).
Obesity (continued). "To investigate the pattern and regulation of ANGPTL2 expression in human adipose tissues in obesity and its related diseases, we recruited 32 non-diabetic and 13 type 2 diabetic obese women and 32 normal-weight women." (PMID 30228336, 2018). "However, unlike adipose tissue ANGPTL2 mRNA expression, serum ANGPTL2 was higher when type 2 diabetes was present in addition to obesity." (PMID 30228336, 2018).